SHOX2 (SHOX homeobox 2)
Diseases named in the same sentence as SHOX2 in open-access papers (continued):
Sharing a sentence is not in itself a finding about the gene and the disease.
lung carcinoma (continued). "The positive detection rates of each marker in lung carcinomas ranked from high to low were 69.1% (HOXA9), 64.7% (SHOX2), 45.6% (RASSF1A), 30.9% (cytology), and 20.6% (SEPTIN9)." (PMID 36176402, 2022). "Among the candidate genes, SHOX2 and RASSF1A are the most sensitive molecular markers for the early detection of lung cancer." (PMID 35651679, 2022). "The LungMe® SHOX2 and RASSF1A Assay (Tellgen Corporation, China) has been reported to be highly sensitive and specific for lung cancer using bronchial aspirates." (PMID 36176402, 2022). "The data showed that the sensitivity of the SHOX2, RASSF1A and PTGER4 methylation panel in blood plasma was 87.0% in lung cancer group." (PMID 34408226, 2021). "SHOX2 expression was higher in most cancers, including sarcoma, brain and CNS cancer, head and neck squamous carcinoma (HNSC), and lung cancer." (PMID 34262939, 2021). "The SHOX2 and RASSF1A methylation detection greatly improves the sensitivity of lung cancer detection." (PMID 33425721, 2020). "The results manifest for the first time that, the assessment of SHOX2 and RASSF1A methylation levels in FFPE tissue sample can improve the accuracy of lung cancer diagnosis compared with conventional pathology alone." (PMID 33425721, 2020). "The presented results show for the first time that the assessment of SHOX2 and RASSF1A methylation levels in FFPE tissue samples can improve the accuracy of lung cancer diagnosis compared with conventional pathological alone." (PMID 33425721, 2020). "LungMe® is the worldwide first commercialized methylation detection kit comprising SHOX2 and RASSF1A panel for lung cancer detection." (PMID 33425721, 2020). "The significantly higher SHOX2 (A, 4.9 ± 2.7) and RASSF1A (B: 6.5 ± 3.6) DNA methylation (lower ΔCts) can be found in FFPE samples from lung cancer cases in comparison to the benign lesion controls (A, 9.4 ± 0.8; B, 12.9 ± 2.1)." (PMID 33425721, 2020). "In 2017, the Epi proLung® blood-based version for the lung cancer test received the CE-IVD mark, which is based on a combination of the methylation analyses of SHOX2 and PTGER4 (the prostaglandin E receptor 4 gene)." (PMID 31316555, 2019). "Such previous studies identified the RASSF1A, PITX2, SHOX2, TFPI-2, FHIT, p16, CDH13, and APC genes as predictors of recurrence of lung cancers." (PMID 23544068, 2013). "In this study the DNA methylation, gene expression and gene amplification of SHOX2 in matched tumor and normal adjacent tissues (NAT) from 55 lung cancer patients were investigated." (PMID 21426551, 2011). "For example, when the methylation of SHOX2 and RASSF1A is combined for lung cancer diagnosis, the sensitivity reaches 81.0%, and the specificity is 97.4%, significantly outperforming the serum biomarker carcinoembryonic antigen (CEA) with a sensitivity of 30.6% and a specificity of 100.0%." (PMID 40949724, 2025). "DNA methylation analysis of SHOX2 combined with PTGER4 in blood plasma allows detection of lung cancer and differentiation of non-malignant diseases." (PMID 39132504, 2024). "Serving as a powerful complement and extension to conventional methods, the combined analysis of SHOX2 and RASSF1A methylation could enhance the accuracy of lung cancer diagnosis, offering satisfactory sensitivity and specificity." (PMID 38429660, 2024). "The transcriptional regulator SHOX2 plays a role in processing somatosensory information and is a known oncogene that regulates cell proliferation, apoptosis, WNT/β-catenin, and TGF-β signaling pathways in lung cancer." (PMID 36703136, 2023). "Therefore, we aimed to explore the role of SHOX2 and RASSF1A methylation in BFF/BALF for lung cancer diagnosis." (PMID 37182143, 2023). "Methylated SHOX2 and RASSF1A genes are potential biomarkers for lung cancer diagnosis." (PMID 37182143, 2023).
lung carcinoma (continued). "In conclusion, we found that the aberrant promotor methylation of OncoMe (SHOX2, RASSF1A, SEPTIN9 and HOXA9) is a cancer-specific alteration and may be a valuable marker to aid in the differentiation of MPE, even not limited to lung cancer." (PMID 36176402, 2022). "Additionally, the SHOX2 and RASSF1A in BALF show significant methylation differences before and after the surgical treatment of early lung cancer (p < 0.0001)." (PMID 35651679, 2022). "The combined detection of SHOX2, RASSF1A and PTGER4 gene methylation in plasma improved detection sensitivity in lung cancer diagnosis compared to previous studies, and achieved high sensitivity across all histological subtypes of lung cancer." (PMID 34408226, 2021). "Notably, the SHOX2, RASSF1A, and PTGER4 methylation panel in plasma achieved a high sensitivity of 82.5% in stage I and 90.5% in stage II lung cancer patients, respectively." (PMID 34408226, 2021). "This quantitative analysis shows that the degree of SHOX2 methylation is correlated with the stage of lung cancer, whereas the correlation is not observed in the case of RASSF1A methylation." (PMID 33425721, 2020). "Although nonsignificant, the methylation levels of SHOX2 in patients with lung cancers were higher than those in healthy controls." (PMID 31888670, 2019). "The blood levels of individual biomarkers [IDH1, DNA methylation of short stature homeobox 2 gene (SHOX2), and prostaglandin E receptor 4 gene (PTGER4)] were measured and statistically analyzed in samples from healthy controls and patients with lung cancer." (PMID 31888670, 2019). "The highest SHOX2 methylation levels were found in samples from patient with breast (SHOX2: 363%, SEPT9: 0%), a patient with stomach (SHOX2: 270%, SEPT9: 22%) and a patient with lung cancer (SHOX2: 51%, SEPT9: 16%)." (PMID 24386354, 2013). "SHOX2 expression, gene copy number and DNA methylation were determined in lung tumor tissues and matched morphologically normal adjacent tissues (NAT) from 55 lung cancer patients." (PMID 21426551, 2011). "The hypermethylation of SHOX2 in lung cancer tissue has otherwise not been described in the literature so far." (PMID 21047392, 2010). "SHOX2 DNA methylation allowed for an accurate detection of lung cancer patients even in this group of cytologically negative patient samples." (PMID 21047392, 2010). "Additionally, the performance of SHOX2 methylation in formalin-fixed, paraffin-embedded (FFPE) samples was evaluated, showing a sensitivity of 78.1% and a specificity of 92.1% in distinguishing lung cancer from benign lesions." (PMID 40191732, 2025). "Gene methylation levels of SHOX2 and RASSF1A display higher specificity and sensitivity for early lung cancer detection than the traditional cytological method as well as dual genes (RASSF1A-RARβ2, SHOX2-PTGER4, and p16-RARβ2, which could become possible biomarkers for early diagnosis." (PMID 38068961, 2023). "Therefore, methylated SHOX2 and RASSF1A genes may be promising tumor markers in lung cancer diagnosis." (PMID 37182143, 2023). "Prof. Gunter had confirmed the discriminative performance of the SHOX2/PTGER4 DNA methylation marker panel with AUC values of 0.91–0.98, in a population with up to 61% non-Ade lung cancers." (PMID 31888670, 2019). "Several combinations of differentially methylated gene promoter regions were found to be more effective than single gene promoters (RASSF1A/RARB2, SHOX2/PTGER4, RTEL1/PCDHGB6, HOXD10/PAX9/PTPRN2/STAG3, APC/AIM1/CDH1/DCC/MGMT/RASSF1A) in distinguishing lung cancer patients from noncancerous controls." (PMID 36765815, 2023). "Furthermore, SHOX2 methylation, but not RASSF1A methylation, was correlated with the stages of lung cancer." (PMID 36691467, 2023).
Pleural effusion (10 papers, 2013 to 2025). The presence of an excessive amount of fluid in the pleural cavity. "For instance, low SHOX2 DNA methylation values predicted a shorter progression-free survival following resection in non-small cell lung cancer, whereas hypermethylation of SHOX2 in pleural effusions was associated with an adverse outcome." (PMID 27999621, 2016). "The combined detection of SHOX2 and RASSF1A gene methylation with CEA level in pleural effusion has a high diagnostic value for malignant pleural effusion." (PMID 37158875, 2023). "To avoid issues of multiple testing due to low patient numbers, we transferred the cutoff established on pleural effusions to the ascites samples (10 % SHOX2 methylation)." (PMID 26937257, 2016). "Thus, SHOX2 methylation has been suggested as a biomarker in body fluids, e.g., blood plasma, bronchial aspirates, ascites, and pleural effusions." (PMID 27999621, 2016). "In another ongoing study we participated in, 9% of the pleural effusion samples from tuberculosis patients showed positive methylation of PTGER4 and/or SHOX2 genes." (PMID 40777114, 2025). "This study aimed to evaluate the value of DNA methylation combined with CEA level in diagnosing malignant pleural effusion by detecting SHOX2, RASSF1A gene methylation, and CEA level in pleural effusion." (PMID 37158875, 2023). "Methylated SHOX2 has been studied previously for detecting LC in lymph node samples obtained by EBUS-TBNA, in bronchial aspirates, pleural effusion, plasma, and tumor tissue." (PMID 31547177, 2019). "The positivity of both DNA methylation markers in ascites caused by different cancer entities confirms the results of DNA methylation analyses of SHOX2 and SEPT9 in the cellular fraction of pleural effusions." (PMID 26937257, 2016). "The detection of quantitative SHOX2 and SEPTIN9 methylation levels have successfully applied to the diagnosis of colonic adenomas and the detection of malignant cells in pleural effusions and ascites." (PMID 41477641, 2025). "We detected the methylation of the SHOX2 gene and RASSF1A gene in two groups of pleural effusion." (PMID 37158875, 2023). "An earlier study in which SHOX2 and SEPT9 methylation was determined in the cellular fraction of pleural effusions revealed an elevated SHOX2 background methylation—even in patients without malignancies—while SEPT9 methylation was solely found in cancer patients." (PMID 26937257, 2016). "The sensitivity, specificity, accuracy, positive predictive value, negative predictive value, and Youden’s index of SHOX2, RASSF1A gene methylation, CEA, and their combined detection in pleural effusion for the diagnosis of malignant pleural effusion were calculated, respectively." (PMID 37158875, 2023).
breast carcinoma (9 papers, 2010 to 2025). "SHOX2 overexpression has been linked to hepatocellular carcinoma tumor recurrence and poor breast cancer survival." (PMID 37091145, 2023). "Our previous studies showed that high expression levels of SHOX2 are significantly associated with mesenchymal-like cell shape and poor survival of breast cancer patients." (PMID 34465361, 2021). "The expression level of SHOX2 is strongly associated with poor distant metastasis-free survival in breast cancer patients and inactivation of SHOX2 suppresses breast tumor growth and metastasis in mice." (PMID 34465361, 2021). "To elucidate the mechanisms underlying SHOX2-mediated metastasis, we examined the correlation between the expression of SHOX2 and metastatic drivers using the gene expression data from the TCGA breast cancer cohort." (PMID 34465361, 2021). "In the present study, our TCGA data established the connection between SHOX2 abundance and a high gene expression signature of Gene Hallmark EPITHELIAL_MESENCYMAL_TRANSITION in breast cancer patients, providing a strong rationale for targeting SHOX2 in metastatic breast cancer." (PMID 34465361, 2021). "Based on these results, we found a clinical connection between SHOX2 expression and aggressive, metastatic characteristics in breast cancer patients." (PMID 34465361, 2021). "SHOX2 are highly expressed in mesenchymal-like breast cancer cell lines while are either low or undetectable in epithelial-like breast cancer cell lines." (PMID 34465361, 2021). "Together, these results indicate the involvement of SHOX2 in breast cancer progression, likely due to its role in enhancing the proliferation and invasion potential of cancer cells." (PMID 34465361, 2021). "As a direct miR-375 target, SHOX2 promotes the epithelial-to-mesenchymal transition (EMT) of breast cancer cells through the up-regulation of transforming growth factor β (TNF-β) signaling." (PMID 34465361, 2021). "To gain initial insight into the role of SHOX2 expression in breast cancer, we analyzed TCGA breast cancer cohort to determine how SHOX2 expression corresponded with specific clinical characteristics." (PMID 34465361, 2021). "The results of this study suggest that SHOX2 cooperates with STAT3 to drive breast cancer metastasis through upregulating the metastasis-promoting gene WASF3." (PMID 34465361, 2021). "Here, we show for the first time that SHOX2 drives breast cancer metastasis through the regulation of Wiskott-Aldridge Syndrome (WAS) protein family member 3 (WASF3), an actin cytoskeleton controlling and metastasis-promoting gene." (PMID 34465361, 2021). "A systematic evaluation of miRNAs further revealed that SHOX2 expression levels negatively correlate with the expression levels of miR-375, a well-known microRNA involved in the migration and invasion of breast cancer cells." (PMID 34465361, 2021). "Given that our previous studies have demonstrated WASF3 to be the most closely associated with breast cancer invasion and metastasis of the WASF family members, we subsequently focused our attention on the regulation of WASF3 by SHOX2." (PMID 34465361, 2021). "In breast cancer cells, SHOX2 directly activates Wiskott-Aldridge syndrome protein family member 3 (WASF3), a metastasis-promoting gene, at the transcriptional level, leading to a significant increase in metastatic potential." (PMID 34465361, 2021). "Human short stature homeobox 2 (SHOX2), a homeodomain transcription factor, is a novel inducer of epithelial-to-mesenchymal transition in breast cancer cells, though its exact role and underlying mechanisms in metastasis are not well understood." (PMID 34465361, 2021). "Here, we reveal that SHOX2 signaling additionally influences the metastatic process through WASF3/E-Cadherin signaling in breast cancer cells." (PMID 34465361, 2021).
breast carcinoma (continued). "We further demonstrated that STAT3 cooperates with SHOX2 to form a functional immunocomplex on the WASF3 promoter to promote WASF3 transcriptional activity in breast cancer cells." (PMID 34465361, 2021). "For instance, in breast cancer it was identified as targeting short stature homeobox 2 (SHOX2), readily mediating EMT suppression." (PMID 27187371, 2016). "The mechanisms by which SHOX2 contributes to the development and progression of breast cancer, however, remain largely unknown." (PMID 34465361, 2021). "The transcriptional regulation of WASF3 by SHOX2 encouraged us to determine whether WASF3 was a functional downstream target of SHOX2 during its promotion of breast cancer metastasis." (PMID 34465361, 2021). "Furthermore, this gene expression signature of Gene Hallmark EPITHELIAL_MESENCYMAL_TRANSITION significantly correlated with SHOX2 expression (r = 0.7377) in TCGA breast cancer patients." (PMID 34465361, 2021). "Overall, however, our findings provide new mechanistic insight into SHOX2-dependent cell invasion and metastasis and hint that inhibiting it may represent a promising therapeutic strategy for breast cancer patients." (PMID 34465361, 2021). "TCGA analysis was performed to identify the clinical relevance of SHOX2 in breast cancer." (PMID 34465361, 2021). "To investigate the importance of SHOX2 expression in the tumorigenesis and metastasis of human breast cancer, we established orthotopic breast cancer xenografts by injection of SHOX2 knockdown and knockdown control MDA-MB-231 cells into the mammary fat pad of female NSG mice, respectively." (PMID 34465361, 2021). "Interestingly, SHOX2 expression is frequent in various different types of tumors, among them neuroblastomas, breast cancer and squamous cell carcinomas of the lung (Genbank information)." (PMID 21047392, 2010). "To investigate whether the specific binding of SHOX2 to the WASF3 promoter was required for the transcriptional activation of WASF3, we carried out ChIP assays which demonstrated the specific occupancy of SHOX2 at the WASF3 promoter-binding sites in breast cancer cells." (PMID 34465361, 2021). "In this context, STAT3 collaborates with SHOX2 to form a functional immunocomplex, thereby enhancing the transcriptional activity of WASF3 in breast cancer cells and promoting breast cancer metastasis." (PMID 38429660, 2024). "For example, the lncRNA IGF2-AS, as an antisense gene of IGF2, inhibits the tumorigenesis of breast cancer by epigenetically regulating IGF2 and affects the metastasis and prognosis of gastric adenocarcinoma by sponging miR-503 to regulate SHOX2." (PMID 35675043, 2022). "The data presented here provide the first evidence that the transcriptional activation of WASF3 is synergistically regulated by SHOX2 and STAT3 through their assembly of a functional complex on the WASF3 promoter in breast cancer cells." (PMID 34465361, 2021). "Recent work has identified SHOX2, an inducer of EMT in breast cancer cells, as a novel miR-375 target, suggesting a possible mechanism for restoration of the epithelial phenotype in BCD cells by miR-375." (PMID 25875172, 2015). "Although a high SHOX-2 expression was correlated to enhanced migration and invasion capacities for breast cancer cells through a SHOX-2/STAT3/WASF3 axis, no relation has been established between the SHOX-2 expression and fibrinolysis." (PMID 35935486, 2022). "Nevertheless, our study underscores the complexity of WASF3 transcriptional activation and provides evidence that SHOX2 and STAT3 are assembled in the same complex on the WASF3 promoter and act synergistically to promote WASF3 expression in breast cancer cells." (PMID 34465361, 2021). "SHOX2 is reported to activate the TGF-β receptor I (TβR-I) gene through the consensus HOX-binding site in its promoter, leading to EMT induction and invasion through the TGF-β signaling network in epithelial-like breast cancer cells." (PMID 34465361, 2021).
breast carcinoma (continued). "The reported upregulation of SHOX2 by STAT3 activation in Helicobacter pylori-infected gastric cancer cells is a cell type-specific effect given that no elevation in SHOX2 was observed in breast cancer cells following IL6-induced STAT3 activation." (PMID 34465361, 2021). "In this analysis, SHOX2 expression levels were found to be significantly correlated with the expression of two WASF genes, WASF1 and WASF3, suggesting SHOX2 may promote breast cancer metastasis through WASF-mediated signaling." (PMID 34465361, 2021). "Mechanistically, SHOX2 activates signal transducer and activator of transcription 3 (STAT3) and recruits it to the WASF3 promoter, where STAT3 cooperates with SHOX2 to form a functional immunocomplex to promote WASF3 transcriptional activity in breast cancer cells." (PMID 34465361, 2021). "SHOX2 and RASSF1A are not suitable for tissue tracing if it is applied to pleural fluid or blood samples, as they are also positive for breast cancer, gastric cancer, and esophagus cancer." (PMID 38429660, 2024).